USP17L25 (ubiquitin specific peptidase 17 like family member 25)
Description:
Deubiquitinating enzyme that removes conjugated ubiquitin from specific proteins to regulate different cellular processes that may include cell proliferation, progression through the cell cycle, apoptosis, cell migration, and the cellular response to viral infection.
Target class: Enzyme; Hydrolase
Gene: Protein-coding gene on chromosome 4 (9,329,911 to 9,331,503, forward strand). Ensembl gene ENSG00000230430.
Subcellular location: Nucleus, nucleolus; Endoplasmic reticulum
Pathways (Reactome):
Metabolism of proteins: Ub-specific processing proteases
Gene Ontology:
Molecular function: cysteine-type deubiquitinase activity; hyaluronic acid binding; RNA binding
Biological process: positive regulation of epithelial cell apoptotic process; protein deubiquitination involved in ubiquitin-dependent protein catabolic process; regulation of apoptotic process; protein deubiquitination
Cellular component: nucleolus; nucleus; endoplasmic reticulum
Homologues: Paralogues in human: USP17L24 (100% identical), USP17L26 (100% identical), USP17L27 (100% identical), USP17L28 (100% identical), USP17L29 (100% identical), USP17L30 (100% identical), USP17L5 (99% identical), USP17L20 (99% identical), USP17L11 (99% identical), USP17L17 (99% identical), USP17L18 (99% identical), USP17L22 (99% identical), and 59 more.